DUSP11 (dual specificity phosphatase 11)
Description:
Possesses RNA 5'-triphosphatase and diphosphatase activities, but displays a poor protein-tyrosine phosphatase activity. In addition, has phosphatase activity with ATP, ADP and O-methylfluorescein phosphate (in vitro). Binds to RNA. May participate in nuclear mRNA metabolism.
Synonyms: PIR1
Tractability: PROTAC: ubiquitination databases record sites on it.
Gene: Protein-coding gene on chromosome 2 (73,761,782 to 73,780,173, reverse strand). Ensembl gene ENSG00000144048.
Subcellular location: Nucleus; Nucleus speckle
Subcellular location (Human Protein Atlas): Nucleoli fibrillar center; Nucleoplasm; Cytokinetic bridge
Gene Ontology:
Molecular function: phosphatase activity; polynucleotide 5'-phosphatase activity; protein tyrosine phosphatase activity; RNA binding; hydrolase activity
Biological process: protein dephosphorylation; RNA processing
Cellular component: mitochondrion; nuclear speck; nucleoplasm; nucleus
Genetic constraint (gnomAD): Loss-of-function variants: 14 observed, 17.01 expected, observed/expected ratio (o/e) 0.82, 90% interval 0.54 to 1.29. The upper end of that interval is the gene's LOEUF score, 1.29, which puts it in group 5 of 6, group 1 being the genes least tolerant of losing a copy. Missense variants: 261 observed, 244.54 expected, observed/expected ratio (o/e) 1.07, 90% interval 0.96 to 1.18. Synonymous variants: 107 observed, 87.97 expected, observed/expected ratio (o/e) 1.22, 90% interval 1.04 to 1.43.
Homologues: Orthologues: chimpanzee DUSP11 (99% identical), macaque DUSP11 (95% identical), dog DUSP11 (79% identical), rabbit DUSP11 (78% identical), guinea pig DUSP11 (78% identical), mouse Dusp11 (69% identical), rat Dusp11 (69% identical), pig DUSP11 (65% identical), zebrafish dusp11 (37% identical), tropical clawed frog dusp11 (36% identical). Paralogues in human: RNGTT (26% identical).
Diseases named in the same sentence as DUSP11 in open-access papers:
DUSP11 is named in the same sentence as 14 diseases in open-access papers, as found by Europe PMC text mining. Sharing a sentence is not in itself a finding about the gene and the disease. The quoted sentences say what the papers report.
virus infection (4 papers, 2019 to 2025). "The role of DUSP11 in virus infection is context-dependent, however, previous work from our lab has shown that some viruses (e.g., + ssRNA sindbis virus (SINV) and -ssRNA vesicular stomatitis virus (VSV)) benefit from DUSP11 activity during infection." (PMID 40258008, 2025). "While the function during native APV/APV-related virus infection has yet to be elucidated, vDUSP11s share conserved functions in modulating the immune response, as seen with host DUSP11." (PMID 40258008, 2025). "However, so far, there are only limited contexts reported where DUSP11 activity matters during virus infection." (PMID 40258008, 2025). "Although there are no known biochemical activities of DUSP11 other than phosphatase activity, it was formally possible that DUSP11 had unknown activities that could account for its role in promoting virus infection." (PMID 33184222, 2020). "While these results do not rule out a contribution of host RNAP III RNAs to protection from virus infection in DUSP11 knockout cells, they do demonstrate that analogous to host-derived endogenous RNAs, viral transcripts known to activate RIG-I are modulated by DUSP11 during infection." (PMID 33184222, 2020). "To test the hypothesis that DUSP11-deficient cells have reduced viral infection due to enhanced RIG-I signaling, we determined whether DUSP11 deficiency would result in enhanced interferon expression during virus infection." (PMID 33184222, 2020). "Therefore, we determined if virus infection altered DUSP11 subcellular localization." (PMID 33184222, 2020). "This may be due partly to viral infection-induced reduction in the level of cellular triphosphatase DUSP11, which dephosphorylates the 5′ppp group on the vault RNAs, as they could only be immunogenic (in the absence of viral infection) by the addition of the 5′ppp group." (PMID 31379819, 2019). "Virus infection of cells lacking DUSP11 results in a higher proportion of triphosphorylated viral transcripts and attenuated virus replication, which is rescued by reducing RIG-I expression." (PMID 33184222, 2020). "Consistent with the known functions of host DUSP11, we have shown that expression of vDUSP11s: 1) reduces levels of endogenous RNAPIII transcripts, 2) reduces a cell’s sensitivity to 5’pppRNA-mediated immune activation, and 3) restores virus infection defects seen in the absence of DUSP11." (PMID 40258008, 2025). "We hypothesized that APVs/APV-related viruses have acquired vDUSP11 to mimic host DUSP11’s immunomodulatory properties, which alter the sensitivity of RIG-I activation and modulate RNAP III transcripts upregulated in the context of various virus infections." (PMID 40258008, 2025).
autoimmune disease (2 papers, 2018 to 2026). A disorder resulting from loss of function or tissue destruction of an organ or multiple organs, arising from humoral or cellular immune responses of the individual to their own tissue constituents. "Given the role of DUSP11 in preventing the accumulation of endogenous RIG-I ligands it will be necessary to determine whether it is associated with autoimmune disease." (PMID 30451863, 2018). "Downregulation of DUSP1, DUSP3, DUSP11, and DUSP22, as well as upregulation of DUSP4, DUSP6, and DUSP23 are involved in human autoimmune diseases." (PMID 42087139, 2026).
breast carcinoma (1 paper, 2020). "To determine whether DUSP11 would influence RIG-I sensitivity toward endogenous DAMP RNAs, we cocultured human foreskin fibroblasts (HFF) with breast cancer cells (MDA-MB-231), with or without knockdown of DUSP11, and assayed for enhanced interferon transcript induction." (PMID 33184222, 2020).
glioma (1 paper, 2024). A benign or malignant brain and spinal cord tumor that arises from glial cells (astrocytes, oligodendrocytes, ependymal cells). "Moreover, DUSP11, LPIN3, MTMR11, HDDC2, and PLPPR3 have not been queried for glioma-related studies." (PMID 39830513, 2024).
inflammatory bowel disease (1 paper, 2026). A spectrum of small and large bowel inflammatory diseases of unknown etiology. "Additionally, decreased levels of DUSP2, DUSP11, DUSP22, and DUSP28 are associated with human inflammatory bowel diseases." (PMID 42087139, 2026).
lung carcinoma (1 paper, 2021). "MiR-513b-5p targets DUSP11 and is involved in AZIN1-AS1-promoted lung cancer progression." (PMID 34120890, 2021).
peritonitis (1 paper, 2021). Inflammation of the peritoneum (tissue that lines the abdominal wall and covers most of the organs in the abdomen). "Very recently, DUSP11 (dual-specificity phosphatase 11, DUSP11) is reported to inhibit LPS-induced peritonitis in mice." (PMID 34884814, 2021).
prostate carcinoma (1 paper, 2017). A carcinoma that arises from epithelial cells of the prostate gland. "Significant examples include, a single 14 Kb deletion at chromosome 2: 74,006,259–74,020,290 resulting in a potential novel prostate cancer fusion DUSP11-C2orf11 and a 4 Kb insertion within the CHL1 gene at chromosome 3: 284,661–305,427." (PMID 28423598, 2017). "DUSP11 encodes for a dual specificity phosphatase (DUSP), of which the gene family has been shown to have important roles in the mitogen-activated protein (MAP) kinase pathways in prostate cancer, with changes in DUSP expression associated with prostate cancer cell survival/death." (PMID 28423598, 2017).
infection (6 papers, 2015 to 2025). The state of being infected such as from the introduction of a foreign agent such as serum, vaccine, antigenic substance or organism. "These viral DUSP11 variants (vDUSP11s) can alter immunostimulatory host RNAs, counteract host defenses, and promote infection of a model virus." (PMID 40258008, 2025). "Infection with Kaposi’s sarcoma-associated herpesvirus (KSHV) or human immunodeficiency virus 1 (HIV-1) leads to reduced DUSP11 protein levels and increases in vault and Y RNA association with RIG-I." (PMID 33444401, 2021). "Although DUSP11 can convert structured triphosphate RNAs into monophosphates, and DUSP11 has been implicated as being reduced during infection by some viruses, the physiological role of DUSP11 in the innate immune response is poorly understood." (PMID 33184222, 2020). "Our results identify a context where DUSP11 activity has been co-opted by viruses to alter RNA metabolism and influence the outcome of infection." (PMID 40258008, 2025). "When DUSP11 expression was reduced by siRNA-mediated knockdown, infection of early passage NHDF cells with VSV resulted in an approximately fivefold to 13-fold reduction in virus replication." (PMID 33184222, 2020). "Although DUSP11 remains overwhelmingly nuclear, the detection of cytosolic DUSP11 during infection is consistent with DUSP11 directly acting on viral transcripts localized in the cytosol." (PMID 33184222, 2020). "Infection of cells expressing wild-type DUSP11 resulted in an approximately fourfold enhanced virus replication over control empty vector-expressing cells and an ∼15-fold enhanced virus replication over cells expressing the DUSP11 catalytic mutant." (PMID 33184222, 2020). "Thus, DUSP11 levels are reduced by infection with diverse virus families, implying advantage to the host by increasing the propensity of cells to activate the antiviral response." (PMID 33444401, 2021). "This suggests that infection did not dramatically alter DUSP11 activity associated with the turnover of host RNAP III transcripts." (PMID 33184222, 2020). "Our work identifying triphosphorylated RNAs bound to RIG-I puts forth a model whereby RIG-I dependent sensing is triggered upon an infection-dependent reduction in the expression of the RNA triphosphatase DUSP11, resulting in an accumulation of triphosphorylated RNAs." (PMID 30451863, 2018). "We next explored the possibility that infection could alter DUSP11 biology." (PMID 33184222, 2020). "Finally, we tested whether DUSP11 depletion, and the resultant increase in triphosphoryated RNAs, is sufficient to induce an interferon response outside the context of infection." (PMID 30451863, 2018). "Although a slight overall relative decrease was observed during infection, vault RNA1–3 (vtRNA1–3) and Y1 RNA levels remained higher in DUSP11 KO cells." (PMID 33184222, 2020). "Infection of cells lacking DUSP11 with vesicular stomatitis virus (VSV) results in a higher overall abundance and proportion of 5′-triphosphorylated VSV leader RNA, a well characterized small RNA RIG-I agonist." (PMID 33444401, 2021). "Given that our above data demonstrate that DUSP11 dampens RIG-I-mediated antiviral signaling, we next investigated whether exogenous viral transcripts expressed during the course of infection are altered by the triphosphatase activity of DUSP11." (PMID 33184222, 2020). "Along these lines, it remains possible that the reduced DUSP11 levels observed during KSHV and HIV infection may be mediated in part by the host response to infection." (PMID 33184222, 2020). "In most cases in uninfected states, we observed that cells expressing only the empty vector (EV) showed a slight increase in expression of either ISG15 or IFN-β mRNA under mock infection conditions, consistent with an increased propensity for immune activation in the absence of DUSP11." (PMID 40258008, 2025).
infection (continued). "However, it remains possible that the host response to infection can contribute to the negative control of DUSP11 that occurs during infection with HIV and other viruses." (PMID 33444401, 2021).
cancer (4 papers, 2018 to 2021). A tumor composed of atypical neoplastic, often pleomorphic cells that invade other tissues. "More studies on the expression profile of DUSP11 in cancer would help improve the therapeutic use of its potential inhibitor." (PMID 34660327, 2021). "Our results expand the understanding of the role of the DUSP family in cancer, and indicates DUSP11 as a potential drug target of CCA." (PMID 34660327, 2021). "The studies of DUSP11 in cancer are very few and the role of DUSP11 in tumor progression is nearly in vacancy." (PMID 34660327, 2021). "DUSP11 was considered to participate in cancer progression by several previous studies, but its functions and regulation mechanisms in cancer are still unclear to date." (PMID 34660327, 2021). "Knocking down DUSP11 levels in the recipient cancer cells significantly enhanced the magnitude of IFNB1 transcript induction." (PMID 33184222, 2020). "In addition, some reported factors, including E2F5, PTEN/AKT/mTOR signaling, DUSP11, PRPF39, and LARP4, are involved in miR-513b-5p regulated cancer progression." (PMID 34120890, 2021). "In contrast, if molecules can be identified that reduce DUSP11 catalytic activity, promoting the activation of RIG-I, they may hold therapeutic promise for the treatment of some infectious diseases or even cancer." (PMID 30451863, 2018).
tumor (2 papers, 2020 to 2021). "The expression of DUSP11 was detected with qPCR in eight pairs of iCCAs, pCCAs, and dCCAs, as well as their corresponding tumor-adjacent tissues." (PMID 34660327, 2021). "Our work demonstrates that increasing or decreasing DUSP11 levels can alter the level of RIG-I activation that is triggered by coculture of tumor and fibroblast cells." (PMID 33184222, 2020). "As a result, we demonstrated that DUSP11 expression was associated with tumor infiltration and the OS rate in iCCA, but not in pCCA or dCCA." (PMID 34660327, 2021). "DUSP11 expression was associated with tumor infiltration and the OS rate in iCCA, but not in pCCA and dCCA." (PMID 34660327, 2021). "In our study, we investigated the expression of dual-specificity phosphatase 11(DUSP11) in eight pairs of iCCAs, pCCAs, and dCCAs, and their corresponding tumor-adjacent tissues, as well as their tumor-adjacent tissues with qPCR." (PMID 34660327, 2021). "The tissue specificity and functions in tumor of DUSP11 have not been well studied." (PMID 34660327, 2021).
bacterial infection (1 paper, 2019). "It is currently unclear, by which mechanism DUSP11 operates in this bacterial infection, and whether intracellular bacteria affect DUSP11 RNA expression similar to what was reported for the herpes virus KSV." (PMID 31159473, 2019).
DUSP11 also shares sentences with these, for which no sentence is quoted: hemorrhage (1 paper); infectious disease (1).